IL5 (interleukin 5)
Diseases named in the same sentence as IL5 in open-access papers (continued):
Sharing a sentence is not in itself a finding about the gene and the disease.
asthma (continued). "Our study indicates that anti-interleukin-5 therapy is safe and may reduce asthma exacerbation risk, slightly improve FEV1, FEV1%, and quality of life; and decrease blood and sputum eosinophil levels, although PEF, PC20 were not improved or SABA rescue use reduced." (PMID 27875559, 2016). "Furthermore, treatment of experimental animal models of asthma with quercetin caused not only a decrease in interleukin (IL)-5 levels and eosinophil counts in both bronchoalveolar lavage fluid and lung tissues but also bronchial hypersensitivity, which are induced by specific allergen challenge." (PMID 23840245, 2013). "However, two recent clinical trials have shown that anti-IL-5 antibodies actually could relieve symptoms in eosinophil rich, late onset asthma, suggesting that eosinophils can have a pathogenic role in this disease." (PMID 21235798, 2011). "Specifically, upon stimulation, these cells secrete Type 2 cytokines (IL‐4, IL‐5, IL‐9, and IL‐13) which promote Type 2 inflammatory response in the body and lead to characteristic symptoms of asthma and airway remodeling." (PMID 41568067, 2026). "After mepolizumab treatment (a monoclonal antibody targeting IL‐5), there was a significant decrease in CD62LlowiEos levels among patients with severe asthma." (PMID 41568067, 2026). "Type 2 inflammation contributes to the pathogenesis of asthma through the production of cytokines IL‐4, IL‐5, and IL‐13, thereby inducing characteristic features of asthma such as elevated eosinophil levels and airway hyperresponsiveness." (PMID 41568067, 2026). "While IL-5-targeted therapies yield consistent benefit in severe asthma, therapeutic responses in other airway diseases appear to be shaped by local tissue architecture and mixed inflammatory programs." (PMID 42123654, 2026). "The proliferative capacity of ILC2 and the secretion of IL‐5 and IL‐13 are enhanced in individuals with severe asthma." (PMID 41568067, 2026). "In OVA‐induced asthma models, studies have demonstrated that ILC2s contribute to the production of IL‐5 and IL‐13 in the lungs, comparable to Th2 cells, thereby inducing allergic airway inflammation." (PMID 41568067, 2026). "The Th2 inflammatory pathway is frequently upregulated during these infections, associated with increased production of cytokines such as IL-4, IL-5, and IL-13, which aggravate asthma symptoms." (PMID 41738365, 2026). "In contrast to the innate immunity mediated by ILC2s, Th2 cells modulate adaptive immunity that secretes copious amounts of IL‐4, IL‐5, and IL‐13 in an antigen‐dependent manner, thereby playing a pivotal role in Type 2 inflammation in asthma." (PMID 41568067, 2026). "A Bayesian nonlinear mixed effects dose-time response model predicted the depemokimab dose in severe asthma achieving comparable BEC reductions to those observed in mepolizumab (an approved anti-IL-5 biologic) Phase III MUSCA and MENSA trials." (PMID 41556088, 2026). "Biologics targeting type 2 inflammation, including anti-interleukin-5 (anti-IL-5) antibodies, have improved outcomes in severe asthma, but some patients remain symptomatic with apparently persistent severe airflow limitation." (PMID 41853402, 2026). "This pattern is consistent with the emerging view that pediatric non-T2 asthma often reflects a Th1/Th17-skewed, neutrophil-predominant endotype, in contrast to the classic Th2/IL-4/IL-5/IL-13-driven phenotype that dominates many adult cohorts." (PMID 41601686, 2026). "Asthma is mainly driven by type 2 inflammation, with IL-4, IL-5, and IL-13 inducing eosinophilia, IgE production, mucus hypersecretion, and airway remodeling." (PMID 42193381, 2026). "In contrast, adult T2-high asthma remains dominated by Th2 cytokines (IL-4, IL-5, and IL-13) and eosinophilia, showing robust response to biologics and corticosteroids." (PMID 41601686, 2026).
asthma (continued). "Anti-IgE and anti-IL-5 antibodies are now established as part of the standard treatment for severe asthma, with anti-IL-5 therapies proving highly effective in severe eosinophilic asthma." (PMID 40149465, 2025). "IL-5 enhances the recruitment of eosinophils to the lungs, where they contribute to airway inflammation and hyperresponsiveness, key features of asthma and ALI." (PMID 40872499, 2025). "Anti-IL-5 treatment induces a rebalancing of Treg and T effectorcells in patients with severe asthma." (PMID 40303400, 2025). "The imbalance between Th2 and Th1 lymphocytes represents a predominant etiology of asthma, leading to over-production of Th2 cytokines (IL-4, IL-5, IL-13) and a decrease in IFN-γ, driving the pathophysiological changes in asthma." (PMID 40420184, 2025). "Several of these variants (TSLP, BCL2L11, IL5, IRF1) are shared with severe asthma and peripheral eosinophil count traits, reinforcing the concept that the eosinophilic form of EGPA lies within a broader allergic/type 2 inflammatory spectrum." (PMID 41303621, 2025). "While multiple endotypes of asthma have been described, the most common is allergic asthma, characterized by the production of the type 2 cytokines IL-4, IL-5, and IL-13 following allergen exposure." (PMID 41256356, 2025). "For instance, blocking the action of IL-4, IL-5, and IL-13 with monoclonal antibodies has shown a reduction in airway inflammation and an improvement in asthma symptoms." (PMID 40370530, 2025). "ILC2 and Th2 cells secrete large amounts of type 2 cytokines (T2), IL-4, IL-5, and IL-13, which are key drivers of asthma pathogenesis." (PMID 40370530, 2025). "Th2 cells subsequently produce the characteristic cytokines of type 2 inflammation—IL-4; IL-5; and IL-13—which coordinate the allergic and eosinophilic responses in asthma." (PMID 40564060, 2025). "This study aimed to evaluate clinical improvement and remission in patients with severe asthma treated with anti-IL-5 and anti-IL-5R antibodies over a period of 12 months." (PMID 40804423, 2025). "Type 2-high asthma, characterized by IL-5-driven eosinophilia, prompted the development of long-lived CAR T cells engineered with IL-5 as the targeting domain." (PMID 40260258, 2025). "Type 2high asthma, which accounts for the majority of asthma cases, is driven by Th2 cells that produce cytokines such as IL-4, IL-5, and IL-13." (PMID 41145900, 2025). "Interleukin-5 (IL-5): This cytokine is crucial for the development, activation, recruitment, and survival of eosinophils, which are a defining feature of type 2-high asthma." (PMID 40564060, 2025). "The classical asthma immune response is primarily driven by allergen-specific Th2 and type 2 innate lymphoid cells, which produce mainly IL-4, IL-5, and IL-13." (PMID 40573126, 2025). "Compared with control mice, IL-4, IL-5, and IL-13 concentrations were significantly increased in mice with asthma." (PMID 40343297, 2025). "IL-5 is important in asthma pathogenesis since it contributes to the recruitment and activation of eosinophils." (PMID 40095032, 2025). "In contrast, elevated FeNO in asthma reflects eosinophils, which release toxic potent inflammatory cytokines such as IL-4, IL-5, and IL-13 that induce airway alterations termed sensitization and swelling." (PMID 40662069, 2025). "In severe asthma, biological treatments that primarily target IL-5 have increased our understanding of the significant roles of eosinophils." (PMID 39962262, 2025). "When various biological agents relate to IgE, thymic stromal lymphopoietin (TSLP) and Th2 cytokines (IL-4, IL-5, IL-13) are added to intensive controller medications; these agents are somewhat effective for a subgroup of patients with severe asthma." (PMID 40001485, 2025). "In patients with asthma, it is now well established that anti‐IL‐5 therapy is more effective in those with elevated blood (> 150 cells/μL) and sputum (> 3%) eosinophil levels." (PMID 40781582, 2025).
asthma (continued). "Animal studies revealed that 4-methylpentanoic acid, generated via branched-chain amino acid metabolism, was elevated in asthma models and positively correlated with IL-5 and IL-13 expression." (PMID 41229685, 2025). "This strategy is thought to have saved Aventis (now Sanofi Aventis) millions of dollars by identifying interleukin (IL)-5 as an unfeasible target for human asthma, despite encouraging preclinical data in animals." (PMID 39981184, 2025). "Depemokimab is an ultra-long-acting anti-IL-5 mAb given twice yearly that reduces asthma exacerbations for patients with severe eosinophilic asthma in the SWIFT1 and SWIFT2 phase 3 trials." (PMID 40863432, 2025). "The hallmark of the Th2-high asthma was IL4, IL5, and IL13, and the mouse Elisa kit was used to screen the Th2 cytokines in BALF and serum of different stages mouse models first (data not shown)." (PMID 40503233, 2025). "Type‐2‐high asthma has been characterized by elevated airway or blood eosinophils and high levels of Th2 cytokines IL‐4, IL‐5 and IL‐13 in the airways produced by both T cells and ILCs." (PMID 40105091, 2025). "Currently, the severe asthma and nasal polyposis phenotype is the typical expression of eosinophilic inflammation, which implies the use of anti-IL-5 or anti-IL-5 receptor biologic therapies, as well as anti-IL-4R receptor therapy." (PMID 40649123, 2025). "For example, Leptotrichia (ASV39), which was enriched in asthma, exhibited a strong correlation with the blood IL-5 levels." (PMID 40871265, 2025). "Understanding this pathway has enabled researchers to develop anti–IL-5 therapies as novel treatments in IL-5–driven allergic diseases such as severe asthma." (PMID 39844912, 2025). "Clinical trials have been conducted since 2000 with the inhibitor mepolizumab, which was authorized for use in anti-IL-5 therapy for asthma by the Food and Drug Administration (FDA)." (PMID 40136649, 2025). "During asthma development, PNECs stimulate ILC2s to produce IL-5 either through direct cell–cell contact or via secretion of the neuropeptide CGRP." (PMID 41573715, 2025). "This systematic review shows that approximately half of patients with ATS/ERS-defined severe asthma worldwide meet eligibility criteria for at least 1 biologic therapy targeting IgE, IL-5/IL-5Rα, or IL-4Rα." (PMID 41488544, 2025). "In patients with type 2 severe asthma, characterized by eosinophilic or phenoendotypes, monoclonal antibodies have been developed to block key cytokines such as IL-5, IL-4, IL-13, and immunoglobulin E (IgE)." (PMID 39860330, 2025). "Several genes within the cytokine gene cluster on chromosome 5, specifically IL3, IL4, CSF2, TSLP, IL5, RAD50, and IL13, are recognized as potential asthma susceptibility genes due to their roles in inflammatory regulation among sensitized asthma patients." (PMID 41001556, 2025). "The S1P2 antagonist JTE-013 decreases eosinophil counts and Th2 cytokine (IL-4, IL-5) levels in BALF in allergen-challenged mice (animal model for asthma)." (PMID 40001485, 2025). "Mepolizumab, a systemic anti–IL-5 therapy, has been shown to be effective as an add-on treatment in both SA and CRSwNP, with more literature available on asthma outcomes than on CRSwNP." (PMID 39554605, 2025). "Group 2 innate lymphoid cells (ILC2s) promote the recruitment of eosinophils by secreting large amounts of type 2 cytokines (IL-5 and IL-13), thus triggering the main feature of asthma, pathological inflammation." (PMID 40451928, 2025). "Mepolizumab, benralizumab, and reslizumab are biologics that target the IL-5 pathway to treat severe asthma by impairing IL-5 signaling." (PMID 39844912, 2025). "In a study using an animal model of house dust mite–induced asthma, cigarette smoke was found to increase the number of eosinophils, interleukin-5 (IL-5), IL-13, and transforming growth factor-β in bronchoalveolar lavage fluid." (PMID 40443826, 2025).
asthma (continued). "Eosinophils canonically rely on IL-5 for bone marrow maturation, cell activation, and survival, and therefore, both IL-5 and its receptor emerged as treatment targets in asthma." (PMID 39586024, 2025). "Responses to specific biologics (e.g., anti-IgE, anti-IL-5 therapies) also vary markedly among asthma subtypes." (PMID 41573715, 2025). "Th2-high asthma, characterized by elevated levels of IL-4, IL-5, and IL-13 alongside eosinophilic infiltration, typically demonstrates favorable responses to corticosteroids and specific biologics." (PMID 41394843, 2025). "IL-5 is crucial in asthma as it facilitates the maturation, activation, movement, and survival of eosinophils." (PMID 40893770, 2025). "Therefore, we suggest that the increase in the air pollution in current world, as well as the frequency of asthma or hypereosinophillic syndromes, could be associated with the decreased expression of IL5 in our data, as an evolving evolutionary factor for protection against environmental antigens." (PMID 40149697, 2025). "The severity of the disease was notably associated with pro‐inflammatory cytokines such as TNF‐α and IL‐5, adding to the growing evidence that asthma cannot be understood through a single phenotypic lens." (PMID 41159221, 2025). "IL-5 is a key cytokine involved in the pathophysiology of asthma, particularly in the context of eosinophilic inflammation." (PMID 40564060, 2025). "As already mentioned, the anti-IL-5 monoclonal antibodies, mepolizumab and benralizumab, have presented a major step forward for patients with eosinophilic severe asthma." (PMID 40217624, 2025). "T2-high asthma is seen in around 50% of patients, who typically have eosinophilic inflammation mediated by cytokines including IL-4, IL-5, and IL-13, with enhanced levels of immunoglobulin E (IgE) often present." (PMID 41440490, 2025). "After establishing the asthma model, the levels of IL-5, IL-13, MCP-1, TNF-α, and eotaxin significantly increased in the PLA group compared with those in the NOR group (P < 0.01), while the IL-10 level significantly decreased by 42.0% (P < 0.01)." (PMID 39820222, 2025). "The canonical T2 response is driven by CD4+ Th2 cells and group 2 innate lymphoid cells (ILC2s) that secrete IL‐4, IL‐5, and IL‐13, cytokines central to asthma pathobiology." (PMID 41473388, 2025). "As anticipated, the eosinophil-related cytokine IL-5 had the highest mean values in asthma, second highest in COPD, and equivalent levels to control participants in the bronchiectasis and CF groups." (PMID 40876742, 2025). "Mepolizumab and reslizumab, monoclonal antibodies targeting IL-5, are approved for asthma treatment, with their use in COPD currently in a phase 3 trial." (PMID 40355861, 2025). "Type-2-high asthma is characterized by elevated secretion of interleukins IL-4, IL-5, and IL-13, increased eosinophil counts, and higher total immunoglobulin E (IgE) levels." (PMID 41515904, 2025). "Th2-high asthma, one of the most well-characterized endotypes, is driven by IL-4, IL-5, and IL-13-mediated eosinophilic inflammation, airway remodeling, and epithelial dysfunction." (PMID 40503233, 2025). "For decades asthma has been characterized as a chronic airway condition with eosinophils in the sputum and airways, driven by IL-4, IL-5 and IL-13 from type 2 CD4+ T helper cells." (PMID 40821845, 2025). "IL-4, IL-13, and IL-5 production has been demonstrated to induce clinical symptoms of asthma, including eosinophilia and airway hypersensitivity, indicating a clear role for ST2+ CXCR6+ Th2 cells in driving acute allergic disease." (PMID 41256356, 2025). "The current approved anti-IL-5 and anti-IL-5R therapies are effective in reducing eosinophilic inflammation and asthma exacerbations." (PMID 40872499, 2025). "IL-4 and IL-13 play crucial roles in many aspects of airway changes in asthma, whereas IL-5 supports the development and amplification of eosinophilic inflammation and the induction of airway remodeling." (PMID 39962262, 2025).
asthma (continued). "This deficiency elicits pronounced inflammatory responses in pulmonary tissue, characterized by elevated eosinophil counts and increased levels of IL‐5, consequently leading to exacerbated asthma symptoms." (PMID 41473388, 2025). "With the development of asthma, the excessive secretion of Th2 cytokines, such as IL‐4, IL‐5, and IL‐13, is considered the primary driver of immune dysregulation." (PMID 41280738, 2025). "In humans, three main biologics directed toward IL-5 (mepolizumab, reslizumab) IL-5R (benralizumab) have been designed and used as add-on treatments for severe asthma patients with eosinophilic inflammation." (PMID 41145900, 2025). "Monoclonal antibody therapies have transformed the treatment of severe asthma by targeting pathways such as immunoglobulin E (IgE) and interleukin-5 (IL-5)." (PMID 40364149, 2025). "In 2025, ERS/ATS recommends that in adults with severe asthma and a history of exacerbation, measurements of blood eosinophils ≥ 150 cells/uL can be used to initiate anti-IL5 biologic therapy." (PMID 40863432, 2025). "TH2 cytokines mediate key asthma characteristics: IL-5 for tissue eosinophilia, IL-13 for bronchial hyperresponsiveness, and IL-4 plus IL-13 for goblet cell metaplasia." (PMID 40732309, 2025). "T2-high asthma is typically responsive to corticosteroids and targeted biologics such as anti-IgE and anti-IL-5 therapies." (PMID 41278227, 2025). "For children aged 6–11 years, GINA recently added IL-5 antibody therapy as an option, joining omalizumab and dupilumab as step 5 biologics for the treatment of pediatric severe asthma." (PMID 40843371, 2025). "After macrophage depletion, asthma symptoms in mice worsened, as indicated by elevated total cell counts and increased levels of IL-5 and OVA-specific IgE in the bronchoalveolar lavage fluid (BALF), with more severe lung inflammation." (PMID 40342727, 2025). "Consistent with the importance of these mediators in asthma pathophysiology, approved biologic therapies for severe asthma target IgE, IL-4, IL-5, or thymic stromal lymphopoietin." (PMID 41458996, 2025). "In asthma, several cytokines such as IL-4, IL-5, IL-13, and VEGF play key roles in disease pathogenesis by promoting airway eosinophilia, mucus overproduction, bronchial hyperresponsiveness, immunoglobulin synthesis, and angiogenesis." (PMID 40506894, 2025). "Approved asthma biologic antibodies target critical points surrounding the T2 immune response including T2 cytokine signaling (IL-4, IL-5, and IL-13), downstream T2 response (IgE), and upstream T2 initiation [thymic stromal lymphopoietin (TSLP)]." (PMID 39586024, 2025). "The commonality of the action of anti-TSLP and anti-IL-5 treatment in preventing eosinophilic inflammation also provides the rationale for combination therapy in enhancing severe asthma outcomes." (PMID 40283665, 2025). "IL-5 enhances the release of mediators from eosinophils and, as such, contributes to eosinophil-induced tissue damage, airway inflammation, and asthma exacerbation." (PMID 41145900, 2025). "Targeting IL-5 has become an important therapeutic strategy in asthma, particularly for patients with severe eosinophilic asthma who are not adequately controlled by conventional therapies like ICS or bronchodilators." (PMID 40564060, 2025). "IL-4 released from allergen-bound Th2 cell stimulates the release of IL-4, IL-5, and IL-13, promotes IgE production from B cells, and accelerates inflammation in asthma patients." (PMID 40323927, 2025). "In studies conducted using ovalbumin-induced asthma models, tectorigenin reduced eosinophil infiltration and serum IL5 levels, indicating its ability to control inflammation and eosinophilia-related issues in asthma." (PMID 40598285, 2025).